PRAMEF2 (PRAME family member 2)
Synonyms: FLJ43580; DJ845O24.3
Tractability: PROTAC: ubiquitination databases record sites on it.
Gene: Protein-coding gene on chromosome 1 (12,857,086 to 12,861,909, forward strand). Ensembl gene ENSG00000120952.
Gene Ontology:
Molecular function: ubiquitin-like ligase-substrate adaptor activity
Biological process: proteasome-mediated ubiquitin-dependent protein catabolic process; negative regulation of apoptotic process; negative regulation of cell differentiation; negative regulation of DNA-templated transcription; positive regulation of cell population proliferation
Cellular component: Cul2-RING ubiquitin ligase complex; cytoplasm
Genetic constraint (gnomAD): Loss-of-function variants: 35 observed, 36.1 expected, observed/expected ratio (o/e) 0.97, 90% interval 0.74 to 1.28. The upper end of that interval is the gene's LOEUF score, 1.28, which puts it in group 5 of 6, group 1 being the genes least tolerant of losing a copy. Missense variants: 562 observed, 516.94 expected, observed/expected ratio (o/e) 1.09, 90% interval 1.01 to 1.17. Synonymous variants: 240 observed, 216.33 expected, observed/expected ratio (o/e) 1.11, 90% interval 1 to 1.24.
Homologues: Orthologues: rat Pramef8 (43% identical), mouse Pramel12 (43% identical), mouse Pramel13 (41% identical), mouse Pramel21 (40% identical), mouse Pramel11 (40% identical), mouse Pramel24 (40% identical), rat Pramef12 (40% identical), mouse Pramel20 (39% identical), rat LOC120103107 (39% identical), mouse Pramel16 (39% identical), mouse Pramel28 (39% identical), mouse Pramel31 (39% identical), and 78 more. Paralogues in human: PRAMEF1 (94% identical), PRAMEF13 (93% identical), PRAMEF14 (92% identical), PRAMEF18 (61% identical), PRAMEF19 (61% identical), PRAMEF17 (59% identical), PRAMEF10 (58% identical), PRAMEF33 (58% identical), PRAMEF12 (53% identical), PRAMEF7 (53% identical), PRAMEF8 (53% identical), PRAMEF20 (49% identical), and 12 more.
Diseases named in the same sentence as PRAMEF2 in open-access papers:
PRAMEF2 is named in the same sentence as 1 disease in open-access papers, as found by Europe PMC text mining. Sharing a sentence is not in itself a finding about the gene and the disease. The quoted sentences say what the papers report.
HCMV infection (1 paper, 2022). "Transcripts specifically induced by HCMV infection of TOs included H3Y1 (H3.Y Histone 1), KHDC1L (KH Domain Containing 1 Like), several members of the PRAME Family (PRAMEF2, 8, 12, 14, and 20), and TRIM49A and B (Tripartite Motif Containing 43)." (PMID 35975985, 2022).